NOX4 (NADPH oxidase 4)
Diseases named in the same sentence as NOX4 in open-access papers (continued):
Sharing a sentence is not in itself a finding about the gene and the disease.
melanoma (45 papers, 2011 to 2026). A malignant, usually aggressive tumor composed of atypical, neoplastic melanocytes. "Remarkably, NOX4 inhibitors have shown promises as adjuncts to current therapies, particularly for melanoma patients with BRAF mutations." (PMID 38982044, 2024). "Another example is the association between NOX4 and malignant melanoma in the thyroid identified by MTWAS (P = 8.37 × 10−12)." (PMID 38982044, 2024). "We previously observed that Nox4 expression in BRAF-mutated melanoma cells is related to their metastatic progression." (PMID 37189846, 2023). "We previously demonstrated in BRAF-mutated patients an association between high levels of Nox4 and metastasis occurring at least 1 year after melanoma diagnosis." (PMID 37189846, 2023). "Overexpression of NOX1, uncoupled eNOS, and NOX4 produced ROS in melanoma, linked to the epithelial-mesenchymal transition." (PMID 34777692, 2021). "In order to investigate the interplay between c-met and Nox4, we set up in vitro experiments with a melanoma cell line presenting BRAFV600E mutation, SK-MEL-28." (PMID 33451139, 2021). "Nonetheless, it still remains to be examined how Nox4 derived ROS in BRAF mutated melanoma cells regulate their metastatic progression and drug sensitivity." (PMID 33451139, 2021). "However, our findings on NOX4 are just observational using murine melanoma cells, and further molecular works to establish the causative relation between NOX4 suppression and skin brightening, and confirm it in human melanocytes, are necessary in the future." (PMID 39061944, 2024). "It has been reported that Nox4 was up-regulated in more than half of melanoma cell lines tested or that that expression of Nox4 was detected at least in one third of melanoma patients’ samples, suggesting the association of Nox4 expression with some steps of melanoma development." (PMID 33451139, 2021). "This study suggests that Nox4 inhibitors could be associated to the current therapy used to treat melanoma patients with BRAF mutations." (PMID 33451139, 2021). "NS1 inhibition of STAT3 possibly linked with NOX4 inhibition may reduce cell viability and invasive properties in naïve and resistant melanoma." (PMID 27756874, 2016). "NOX4 overexpression in melanoma cells could be linked with angiogenesis; thus, NS1-induced inhibition of NO and decrease of ROS formed by NOX may modify VEGF levels." (PMID 25296975, 2014). "Melanoma is characterized by its high propensity to metastasize and its proliferation has been linked to an abnormal metabolism, altered redox signalling pathways in which NOX4, uncoupled eNOS and sustained iNOS expression were involved." (PMID 25296975, 2014). "Altogether, NS1 revealed a possible cross-talk between eNOS- and NOX4 –associated pathways in melanoma cells via VEGF, Erk and Akt modulation by NS1 that could be targeted to stop proliferation." (PMID 25296975, 2014). "Data obtained in SK-MEL-28 cell line are consistent with the one obtained in primary BRAF mutated melanoma cells, thus highlighting that the use of a Nox4 inhibitor could potentiate the current therapeutic strategy to treat melanoma patients with BRAF mutations." (PMID 33451139, 2021). "NOX4 generates reactive oxygen species that have been found to reduce melanin formation in mouse melanoma cells, possibly by inhibiting the synthesis of tyrosinase." (PMID 41183498, 2026). "Silencing of NOX4 significantly inhibited basal ROS production and decreased melanoma cell viability through the FAK pathway." (PMID 40864319, 2025). "Recently, the correlation of NOX4 with another pathway involved in the different stages of melanoma, the hepatocyte growth factor (HGF)/c-met axis, has been analyzed." (PMID 39334716, 2024). "According to previous studies that examined the levels of NOX expression in normal human melanocytes (NHMs) and melanoma cell lines, NOX4 was found to play a major role in the melanocyte lineage." (PMID 39061944, 2024).
melanoma (continued). "The NADPH oxidase (NOX4) acts as a survival signal for melanoma cells, maintaining adhesion contacts and cell viability through the focal adhesion kinase (FAK) pathway." (PMID 39519202, 2024). "It has been observed a correlation between the expression level of both c-met and NOX4, indicating them as possible melanoma severity markers, as well as potential cellular markers for a therapeutical strategy to treat this cancer." (PMID 39334716, 2024). "NOX4, highly expressed in metastatic sites, contributes to the transformation of cellular phenotype and affects melanoma cell cycle progression." (PMID 39519202, 2024). "Here, we showed that the development of resistance by both SK-MEL-28 and primary melanoma cells was coupled with an increase in Nox4 expression." (PMID 37189846, 2023). "Among the NOX family, NOX1 and NOX4 isoforms play a major role in melanoma, while NOX5 is also important but still scarcely studied." (PMID 35326089, 2022). "Upregulated NOX4 expression mediated oncogenic proliferation in renal cell carcinoma, melanoma, glioblastoma, and in ovarian and pancreatic cancer." (PMID 35269843, 2022). "The use of DPI and antioxidants blocked melanoma cell proliferation, and the knockdown of NOX4 induced G2-M cell cycle arrest." (PMID 35326089, 2022). "In melanoma cells, NOX4-derived ROS production was described as a promoter of NFκB activation, sustaining cancer progression and metastasis." (PMID 35269843, 2022). "That same group also reported that G6PD works in tandem with NOX4 to activate STAT3 signaling to promote melanoma proliferation and avoid cell cycle arrest." (PMID 35326683, 2022). "The findings hint that Nox4-generated ROS are required for transformation phenotype of melanoma cells." (PMID 33451139, 2021). "NOX4 contributes to the transformed phenotype of melanoma cells by regulating G2–M cell cycle progression." (PMID 34943045, 2021). "Recent studies have also demonstrated that NOX4 plays an important role in melanoma and urothelial carcinoma cell proliferation by regulating cell cycle progression." (PMID 32604782, 2020). "Anyway, the contribution of NOX-4 to transformed phenotype of melanoma cells by modulating G2-M cell cycle progression, suggests that specific signals of NOX family enzymes affect CM development." (PMID 32528879, 2020). "The role of G6PD in cooperation with NADPH oxidase 4 (NOX4) for the support of redox homeostasis has been related to melanoma cells in vitro, indeed targeting both enzymes suppressed cell proliferation." (PMID 33091721, 2020). "At the 3′ end of the locus, at the intergenic space between Tyr and Nox4, we identified a sequence that interacts strongly with the Tyr promoter in melanoma cells and fibroblasts." (PMID 32968154, 2020). "Studies of NOX4 in cancer have focused on malignancies of the brain, breast, bladder, liver, kidney, and ovary, as well as melanoma, primarily in human tumor cell lines." (PMID 28578276, 2017). "Our IHC data have identified esophageal carcinoma as a potential focus for future NOX4 research, joining ongoing but preliminary efforts in bladder, head and neck, and ovarian cancers, and malignant melanoma." (PMID 28578276, 2017). "NOX4-generated ROS are required for transformation phenotype of melanoma cells and contribute to melanoma growth." (PMID 28422720, 2017). "Differential NOX4 staining was observed in bladder, esophagus, head and neck, ovary, and prostate cancers and melanoma compared to corresponding normal tissues." (PMID 28578276, 2017). "Overexpression of NOX4 has been found in diverse types of solid tumors, such as prostate cancer, glioblastoma, liver cancer, and melanoma." (PMID 28422720, 2017). "Defined differential NOX4 expression favoring increased protein in tumor was found for carcinomas of the bladder, esophagus, head and neck, prostate, and ovary as well as malignant melanoma." (PMID 28578276, 2017).
melanoma (continued). "Overexpressed levels of two isoforms of NADPH oxidase (NOX) are active in producing high ROS levels in melanoma: NOX4 and NOX1." (PMID 27756874, 2016). "Of special interest, inhibition of NOX4 suppressed the growth of melanoma cells, indicating that NOX4-generated ROS are required for transformation of melanoma cells." (PMID 25915537, 2015). "Corroborating the NOX4 relevance in MV3 melanoma cell survival, we also observed that NOX4 siRNA induced mitochondrial transmembrane potential dissipation, an early hallmark of apoptosis." (PMID 24911159, 2014). "In melanoma A375 cells, NOX4 was highly expressed compared to low levels in melanocytes, as reported." (PMID 25296975, 2014). "Altogether, the results suggest that intracellular ROS generated by the NADPH oxidase, most likely NOX4, transmits cell survival signals on melanoma cells through the FAK pathway, maintaining adhesion contacts and cell viability." (PMID 24911159, 2014). "NOX4 is linked to proliferation: in the endothelium, it promotes angiogenesis through eNOS activation and in melanoma, NOX4 converted radial to vertical growth by overexpression of Akt." (PMID 25296975, 2014). "Indeed, only the expression level of isoform 4 is higher in metastatic tumors compared with primary melanoma, confirming a potential role of ROS generated by NOX4 in transmitting cell survival signals among melanoma cells." (PMID 39334716, 2024). "Our results indicate that NOX4 could be a shared molecular link between malignant melanoma and thyroid dysfunction." (PMID 38982044, 2024). "The NOX4 gene is altered in 15% of the melanoma patients with the most prevalence for increased mRNA expression and amplification, which corroborates with our data about increased NOX4 expression on melanoma metastasis." (PMID 35326089, 2022). "In particular, upregulated NOX4 protein expression was identified by tissue microarray analysis in a series of malignancies including bladder, esophageal, head and neck, ovarian, and prostate carcinomas and malignant melanoma." (PMID 35269843, 2022). "NOX4 also can regulate the cell cycle to promote the carcinogenesis of melanoma and urothelium." (PMID 36249057, 2022). "NOX4 expression is increased in several melanoma cell lines." (PMID 35326089, 2022). "Actually, in patients showing lymph nodes positivity, the presence of c-met and Nox-4 starts to increase in BRAF mutated cases, but becomes statistically relevant only in cases of distant metastasis, indicating Nox4 as a possible melanoma severity marker as well as c-met." (PMID 33451139, 2021). "Furthermore, AKT induces the expression of the ROS-generating enzyme NOX4 in melanoma cells and growth melanoma cells in mice." (PMID 34777692, 2021). "The pivotal role of Nox4 in melanoma, that this observation suggests, is consistent with data discussed by Meitzler in 2017 where it has been reported that most melanomas showed diffuse positivity of Nox4, even if in a different cellular distribution." (PMID 33451139, 2021). "In melanoma, NOX4 is highly expressed as compared to the low levels in melanocytes." (PMID 34777692, 2021). "Moreover, intracellular ROS generated by the NADPH oxidase, most likely Nox4, transmits cell survival signals on melanoma cells maintaining cell viability." (PMID 33451139, 2021). "Moreover, knockdown of lncRNA growth arrest specific 5 (Gas5) in melanoma enhanced intracellular ROS via increased superoxide anion and NADPH oxidase 4 (NOX4)-oxidized GSH153." (PMID 32709863, 2020). "Similarly, NOX4 knockdown arrests the cell cycle at G2-M stage, thus abolishing melanoma proliferation and tumor formation." (PMID 32850409, 2020). "In addition, Akt induction of NOX4 leads to ROS production which, along with Akt, leads to NF-κB activation, vertical growth of melanoma, and resistance to apoptosis." (PMID 32850409, 2020).
melanoma (continued). "At the same time, high levels of Nox4 activity can coincide with repressed mitochondrial activity in a melanoma model, suggesting that calnexin could use Nox4-mediated ROS production to generally repress mitochondria." (PMID 31547228, 2019). "Furthermore AKT, a kinase downstream of RAS and PI3K signaling, was shown to induce NOX4 expression and thus enhance melanoma cell proliferation." (PMID 30323311, 2019). "NOX4 induction by Akt has been recently reported in melanoma and non‐small cell lung cancer cells." (PMID 28691365, 2017). "Fifty percent of melanomas were high positive for NOX4 (7 of 14 melanomas)." (PMID 28578276, 2017). "In addition to NOX4, uncoupled eNOS and overexpressed NOX1 also produced ROS in melanoma, linked to Epithelial–Mesenchymal Transition." (PMID 25296975, 2014). "Furthermore, our data shed light on NOX4 as a novel pharmacological target for the control of melanoma growth and metastasis." (PMID 24911159, 2014). "NOX-4, a superoxide generating enzyme, is an oncoprotein that is overexpressed in melanoma cells." (PMID 22140508, 2011). "Moreover, NOX2 and NOX4 expression was increased during melanoma progression." (PMID 35326089, 2022). "Also, a prior document demonstrated that UCH-L1 overexpression facilitated cell invasion through increasing cellular ROS and H2O2 levels via deubiquitinating NADPH oxidase 4 (NOX4) in murine metastastic melanoma (B16F10) cells, suggesting the correlation of UCH-L1 and oxidative stress." (PMID 33030206, 2020). "In contrast, in melanoma cells, the role of a switch-deciding transformation from a noninvasive to an invasive phenotype is played by the Akt protein, a kinase that plays a key role in proliferation, cell migration, and apoptosis, which induces NOX4-derived ROS." (PMID 28626501, 2017). "However, NOX4 stands apart from the rest of the family since it appears to be constitutively active, being primarily regulated by its level of expression and addressed as the main source of ROS in a number of melanoma cell lines." (PMID 24911159, 2014). "G6PD regenerates NADPH and silencing of G6PD and NADPH oxidase 4 (NOX4) resulted in G1/S cell cycle arrest and inhibited melanoma cell activity." (PMID 38194707, 2024). "In this regard, we showed that 13% of the melanoma patients have alterations on NOX1 gene, 7% on NOX2, NOX3 and NOX5, and 15% on NOX4." (PMID 35326089, 2022). "In melanomas, NOX1, NOX4, and NOX5 have been confirmed to be expressed, with NOX1 expression consistent throughout progression and NOX4 upregulated during metastasis." (PMID 35326683, 2022). "According to our analysis, 66% of the isoforms presented differential expression on melanoma progression: NOS2, SOD1, NOX4, PRX3, PXDN and GPX1 are increased during melanoma progression, while CAT, GPX3, TXNIP, and PRX2 are decreased." (PMID 35326089, 2022). "Recent understanding of melanoma photobiology has implied the etiological role of NOX enzymes, particularly NOX1 and NOX4." (PMID 29342889, 2018). "NOX1- and NOX4-derived ROS promote HIF-dependent vascularization in prostate cancer and malignant melanomas; however, several reports indicate that ROS-mediated angiogenesis can also occur through an HIF-independent mechanism." (PMID 28626501, 2017). "For example, NOX4 and NOX5 activities have been reported to be involved in the survival of human glioma, melanoma, and prostate cancer cells." (PMID 24911159, 2014). "Modulation of redox-sensitive proteins (peroxiredoxin 3/5, PRX3/PRX5, selenoenzyme 2, TR2, glutathione reductase, GR, and NADPH oxidase 4, NOX4) is suggested as a target for cancer therapy due to their metabolic role in various stages of melanoma, from initiation to metastasis and resistance." (PMID 41197182, 2025).
melanoma (continued). "Another study using ovarian cancer cells demonstrated that NOX4 knockdown decreases HIF-1 and VEGF, which, subsequently, in response, regulates tumor angiogenesis in melanoma cells, showing that ROS operate through a similar mechanism, while Akt stimulates the production of NOX4." (PMID 40801639, 2025). "In malignant melanoma, knockdown of the lncRNA growth arrest-specific 5 (GAS5) led to increased intracellular ROS accumulation by elevating superoxide anion levels and promoting NADPH oxidase 4 (NOX4)-mediated GSH oxidation." (PMID 39595619, 2024). "Here, we show that prolonged exposure of BRAF-mutant melanoma cells to vemurafenib treatment leads to the emergence of drug-resistant melanoma subpopulations characterized by an increase in CD271 expression with induced Akt3 and Nox4 activity and the subsequent EMT process." (PMID 37189846, 2023). "Besides, iNOS, SOD1, NOX4, PRX3, PXDN and GPX1 are generally increased during melanoma progression, while CAT, GPX3, TXNIP and PRX2 are decreased." (PMID 35326089, 2022). "On the other hand, the top downregulated genes formed 4 subgroups and were related to melanogenesis (Wnt5a, Mitf, Pomc, Mc1r, Kit), melanoma (Fgf9, Fgf12, Fgf2), MAPK signaling pathway (Ncam1, Prkcb, Map3k4, Pla2g4a, Mapk14, Mapk11), and aging (Tgfbr1, Il6, Nox4)." (PMID 36555664, 2022). "In this study we investigated the first point, starting from a larger view, analyzing Nox4 and c-met expression in early, late and non-metastatic melanoma patients, then focusing on cellular ROS modulation by HGF/c-met and Nox4 inhibition in vitro." (PMID 33451139, 2021). "Of significance, the antibody to NOX4 reacted with almost all melanomas (14/15, 93%) and none of the normal skin samples (n=8) or the compound nevi (0/2)." (PMID 28578276, 2017). "NS1 decreased specifically NOX4 levels in melanoma and not in healthy melanocytes; detailed mechanistic studies are ongoing." (PMID 25296975, 2014). "Importantly, NOX4 was expressed in almost all of the melanomas studied (14/15, 93%) and none of the normal skin samples (n=8); overexpression of NOX4 was detected in 15/17 (88%) of ovarian carcinomas." (PMID 28578276, 2017). "NOX4 isoform or renal NADPH oxidase (RENOX) is known to be highly expressed in the kidneys and is found in different cell types including neurons, smooth muscle cells, adipocytes, keratinocytes, hematopoietic stem cells, melanoma cells, fibroblasts, osteoclasts, and endothelial cells." (PMID 23840917, 2013). "In this study, we investigated the interplay between HGF, its receptor c-met, and an ROS source (Nox4) in early, late, and nonmetastatic melanoma patients, looking at cellular ROS modulation through the inhibition of HGF/c-met and Nox4 in vitro." (PMID 37189846, 2023).